GZMB (granzyme B)
Diseases named in the same sentence as GZMB in open-access papers (continued):
Sharing a sentence is not in itself a finding about the gene and the disease.
tumor (2,901 papers, 2002 to 2026). "These granzyme B- or IFN-γ-expressing cells were associated with tumor growth inhibition, except for IFN-γ-expressing neutrophils." (PMID 41424839, 2026). "Our results highlight for the first time that SLC7A5-deficient allogenic T cells fail to reject tumor due to impairment in activation, proliferation and GzmB and IFNy expression." (PMID 40399490, 2025). "Of the 57 patients studied, more than 60% had granzyme B-positive tumor that co-expressed CD56, suggesting an association with NK cells or activated cytotoxic T cells." (PMID 40766321, 2025). "The FL imaging signal intensities exhibited a strong association with the expression level of granzyme B, infiltration of T cells, and death of tumor cells." (PMID 40585764, 2025). "Further analysis of tumor-infiltrating lymphocytes (TILs) isolated from MC38 tumors revealed that Usp17la deficiency increased granzyme B (GZMB) and IFN-γ production by cytotoxic CD8+ T cells." (PMID 41023441, 2025). "Both Th2-cells and eosinophils were directly implicated in promoting tumor cell apoptosis, as confirmed by in vitro experiments and elevated levels of soluble GZMB and FAS." (PMID 40725022, 2025). "GZMB, which induces apoptosis and modulates the immune response in the tumor microenvironment, has been associated with improved clinical outcome and overall survival when its methylation is lower." (PMID 40723280, 2025). "This suggests that GZMB is associated with tumor invasiveness, as knocking down or inhibiting GZMB expression significantly reduced tumor invasion." (PMID 41567188, 2025). "The results indicated that more than 60% of them had tumor positive for granzyme B, suggesting a strong association of this expression with tumor characteristics." (PMID 40766321, 2025). "We confirmed that granzyme B production upon anti-PD1 treatment was impaired in tumor-infiltrating AhR-deficient CD8 T cells, contrasting with granzyme B production by WT CD8 T cells being similar in both diet groups." (PMID 41331250, 2025). "Studies also show that Treg cells inhibit the activity of NK and CD8+ T cells through the GZMB-perforin pathway, and GZMB-deficient mice are more effective in clearing both allogeneic and syngeneic tumor cell lines." (PMID 38833021, 2024). "Enterococcus faecium induces synergistic antitumor effects of CTLA4 inhibitors via peptidoglycan fragments, which activate CX3CR1+ monocytes, stimulate cytotoxic lymphocytes to produce granzyme B, and reduce the number of tumor-associated macrophages." (PMID 38715617, 2024). "The increased perforin and granzyme B secretions are associated with the lysing of tumor cells by these activated immune cells, which was further evidenced by a marked reduction in tumor burden." (PMID 38890285, 2024). "While GzmB is required for CD8+ T cells to cause GVHD, GzmB-mediated damage of CD8+ T cells impairs graft-versus-tumor effect." (PMID 38846935, 2024). "Downregulation of granzyme B (Gzmb), Perforin (Prf1) were observed in Prdm1-deficient NK cells, implying decreased anti-tumor ability, which was consistent with increased melanoma metastasis in Prdm1 cko mice." (PMID 39133873, 2024). "These neoantigen-augmented iPSC cancer vaccines remarkably enhanced neoantigen-reactive CD8+ T cell responses and promoted the production of antitumor cytokines such as IFNγ and GzmB to eradicate tumor cells and decrease the risk of distant metastasis." (PMID 38821980, 2024). "NK cells eliminate tumor cells by releasing cytotoxic granules containing granzyme B, and among the immunosuppressive mechanisms associated to NK cells, secreted galectin-1 hinders the tumor-killing effects of these cells by reducing the release of granzyme B." (PMID 38160212, 2024). "It stimulates the action of cytotoxic T lymphocytes, which creates pores in the tumor cell membrane via perforin, consequently allowing granzyme B to enter the cells, where it causes programmed cell death of the tumor cell, apoptosis." (PMID 38542122, 2024).
tumor (continued). "The detection of increased tumor CD8+ T cell infiltrates that are activated and able to produce IFNγ and GZMB and reduced tumor-associated Tregs when CpG-Stat3 siRNA is added to ICB therapy show that CpG-Stat3 siRNA can serve as an effective adjuvant for ICB." (PMID 39618825, 2024). "We investigated the association of CCR8+ Tregs and GzmB+ CD8+ T cells in tumor tissues and further evaluated the prognostic impact of their distribution profiles." (PMID 38783281, 2024). "PRF1 and GZMB encode pore-forming and cytotoxic granules, respectively, involved in the cytotoxic process of NK and T cells against tumor cells." (PMID 39502689, 2024). "Higher production of granzyme B has been associated with lower tumor recurrence and improved survival in CRC patients." (PMID 38250876, 2024). "The reason PI9 overexpression is associated with better tumor survival in a variety of cancer types is likely attributed to its fast-acting irreversible inhibition of GZMB and its consequent deactivation." (PMID 38307835, 2024). "Few residual tumor cells in the post-treatment biopsy were observed and were associated with increased granzyme B+ and PD-L1+ areas, suggestive of an active antitumor immune response." (PMID 38867077, 2024). "Across tumors, the loss of Granzyme B was most pronounced in the iTIL population in the tumor center." (PMID 36562826, 2023). "For instance, Salama and co-authors observed that a higher number of tumor-associated Granzyme B-positive cells is associated with better survival among CRC patients." (PMID 37532996, 2023). "Our data also showed that loss of TCF-1 led to the upregulation of Granzyme B on NKG2D + CD8 T cells which reveals how TCF-1 deficient T cells can kill the tumor cells." (PMID 36562825, 2023). "Of note, a high expression of granzyme B in the tumor periphery was associated with a worse CSS suggesting accelerated disease progression." (PMID 37894418, 2023). "Remarkably, a significantly increased expression of granzyme B in the tumor periphery was associated with a significantly worse cancer-specific survival (CSS) of patients (p = 0.001)." (PMID 37894418, 2023). "Loss of Granzyme B expression was the only mechanism affecting T cell effector function detected in this tumor." (PMID 36562826, 2023). "In CRC, Notch signaling mutations in tumor cells were associated with the enrichment of cytotoxicity-related molecules (e.g., GZMB and PRF1) but also exhaustion-related molecules (e.g., PD-1)." (PMID 37131214, 2023). "We found that ccRCCs harboring a PTEN or BAP1 mutation showed the lowest level of Granzyme B positive tumor-infiltrating lymphocytes (TILs)." (PMID 36562826, 2023). "GSDME can be also cleaved by granzyme B, therefore enhancing the phagocytosis of tumor cells by tumor-associated macrophages, as well as tumor-infiltrating natural killer and CD8+ T lymphocytes." (PMID 37134086, 2023). "In particular, the absence of CD28 was associated with a gradual decline in terms of granzyme-B (GrzB) production from peripheral blood to the NT tissue and the tumor site." (PMID 37898752, 2023). "Tumor cell kill was associated with T-cell activation, proliferation, and production of cytokines, granzyme B, and perforin." (PMID 36271507, 2022). "In accordance, we also observed decreased frequencies of granzyme B producing CD8+ TILs in tumor-bearing Asm-deficient mice, after CD4+ T cell depletion." (PMID 36426850, 2022). "Recent studies have shown that CAR-T cells can quickly causes pyrolysis in targeted tumor cells via GZMB/GSDME/CASP3 pathway." (PMID 35725836, 2022). "Tumor cell kill was associated with cytokine, granzyme B (GZMB), and perforin production, with higher maximum levels after prolonged incubation, except for TNFα, which showed the highest levels after 24 h." (PMID 36271507, 2022).
tumor (continued). "Inflammasome activation in myeloid cells has recently been implicated in the development of CAR T cell–associated CRS, as a consequence of tumor cell pyroptosis induced by CAR T cell–released granzyme B and granzyme A." (PMID 35503659, 2022). "The expression of NCRs is associated with increased production of granzyme B and improved cytotoxicity against tumor cells." (PMID 35747139, 2022). "This increased responsiveness was associated with an increase in the number of tumor-infiltrating CD8+ T cells that expressed the activation marker Granzyme B." (PMID 35082152, 2022). "The increase in granzyme B associated with cytolytic effector function is consistent with greater tumor infiltration by CD8+ T cells." (PMID 36923305, 2022). "CXCR5+CD8 T cells from human peripheral blood mononuclear cells, tumor tissues and tumor associated lymph nodes upregulate effector molecules such as IFNγ, TNFα, granzyme B, and perforin compared to CXCR5−CD8 T cells." (PMID 36314014, 2022). "It has been reported that low GZMB expression is associated with tumour metastasis.NKG7 is a complete membrane protein that is expressed in cytotoxic particles of lymphocytes, and it plays an important role in the development and metastasis of cancer." (PMID 35473583, 2022). "This was associated with less co-localization of tumor cells and cytotoxic T lymphocytes (CTLs), which tended to be in a less activated state as determined by Ki67 and granzyme B expression." (PMID 36077630, 2022). "Taken together, we demonstrate that BRB-E promotes an antitumoral immune landscape consisting of reduced Tregs and associated increase in antitumoral CD8+ T cells with Granzyme B production resulting in reduced tumor burden." (PMID 36016924, 2022). "Chemotherapy can enhance the susceptibility of tumor cells to cytotoxic mediators of T cells such as granzyme B." (PMID 36003765, 2022). "The expression of TNF, IFN-γ, GZMA, and GZMB was higher in the low-risk group, suggesting a stronger cytotoxicity to tumor cells." (PMID 34616734, 2021). "In vivo detection of natural killer (NK) cell activity against tumours was achieved with an activatable chemiluminescent probe containing a granzyme B‐reactive peptide substrate linked to a phenoxydioxetane scaffold through a p‐aminobenzyl alcohol linker." (PMID 33300671, 2021). "Once the tumor is reached, this inhibitory peptide is proteolytically removed by tumor-associated intracellular proteases to render granzyme B active." (PMID 34885176, 2021). "Genes associated with TEff/EMs such as Lgals3, GzmB, and Maf were preferentially expressed in both TEff/EMs and TRMs within the tumor environment." (PMID 33979626, 2021). "GZMB’s putative role in inhibiting tumor growth and invasion is consistent with our observation that endogenous GZMB expression is associated with favorable outcome in adjuvant CRC." (PMID 34972191, 2021). "It directly inhibits the hallmark of cytotoxic T cell anti-tumour immunity by suppressing perforin, granzyme A, granzyme B, Fas ligand and interferon-gamma (IFN-γ) production." (PMID 34771746, 2021). "Hypoxia within the TME was on the one hand reported to increase CTL-mediated tumor cell killing through increasing the packaging of granzyme B. This was associated with prolonged survival in the B16-OVA melanoma mouse model." (PMID 34135885, 2021). "Patients with back mutations in K-Ras and SMAD4 showed higher infiltration of granzyme B+ (GrzB+) T cells in the metastatic tumor microenvironment." (PMID 34204435, 2021). "This study aimed to evaluate LAG-3 expression in NPC and its association with CD3+ tumor-infiltrating lymphocytes (TILs), Granzyme B (GZMB), programmed death ligand 1 (PD-L1), and programmed death 1 (PD-1) expression." (PMID 34454491, 2021).
tumor (continued). "While T-bet ablation restricted the production of IFN-γ, loss of Blimp-1 prevented GzmB expression in response to IL-2, suggesting that two independent programmes required for the polyfunctionality of tumour-reactive cytotoxic CD4+ T cells." (PMID 32680511, 2020). "Granzyme B, involved in cytolytic activity of NK cells, was primed on effectors + TriKE, but in the presence of tumor targets (effectors+tumor+TriKE) these Granzyme B high cells disappeared, likely as a cause of ADCC driven specific degranulation." (PMID 32961861, 2020). "Blimp-1 was critical not only to the expression of GzmB by CD4+ T cells but also to αCTLA-4-driven anti-tumor immunity, as Blimp-1-deficient T cells were unable to control MCA205 tumor growth when mice were treated with αCTLA-4." (PMID 31924474, 2020). "On average, 30% of Blimp-deficient Trp1 cells still expressed GzmB, potentially explaining the tumor control observed in 50% of Ifngr1−/− recipients treated with Prdm1−/−Trp1 cells." (PMID 31924474, 2020). "Consistently, the AUY-922-treated tumor cells were more susceptible to apoptosis induced by granzyme B compared to DMSO-treated tumor cells." (PMID 31992715, 2020). "IFN-γ, TNF-α, and granzyme B are typically associated with antitumor activity of cytotoxic CD8+ T cells via induction of enhanced tumor cell arrest and apoptosis 10, 58-60." (PMID 32206098, 2020). "A recent study has demonstrated that inhba plays a crucial role in inhibiting NK cell proliferation and production of granzyme B thereby leading to impairment of tumor susceptibility to NK cell-mediated killing." (PMID 32194552, 2020). "Research has shown that lenvatinib modulates cancer immunity in the immunocompetent tumor microenvironment by reducing the population of tumor-associated macrophages (TAMs) and increasing the population of interferon-γ– and granzyme-B–producing CD8+ T cells." (PMID 33198671, 2020). "While T-bet ablation restricted interferon-γ (IFN-γ) production, loss of Blimp-1 prevented GzmB expression in response to IL-2, suggesting two independent programs required for polyfunctionality of tumor-reactive CD4+ T cells." (PMID 31924474, 2020). "Not surprisingly, Granzyme B has been proposed as a biomarker to predict patient response to immunotherapies where an upregulation of GZMB would be associated with increased cytotoxic activity and tumor size reduction." (PMID 32983990, 2020). "The decreased tumor size was associated with increased cytotoxic factor granzyme B and the apoptosis marker FAS in tumor tissue supernatants." (PMID 33042110, 2020). "CD103+ CD8+ T cells have been shown to increase tumor necrosis and prevent cancer progression in mice, and CD107a and Granzyme-B expression by CD8+ T cells is known to be a hallmark of cytotoxic T cells that can help eliminate cancer cells." (PMID 32345289, 2020). "Accordingly, mice treated with niclosamide and PD-L1 antibody showed significant delay in tumor growth and increased survival which were associated with the increase of tumor infiltrating T cells and granzyme B release." (PMID 31511071, 2019). "Trastuzumab treatment was associated with a significant increase of tumor-infiltrating NK cells and expression of granzyme B and TiA1 in breast cancer compared with controls." (PMID 32038612, 2019). "Examination of tumor cryosections revealed an increased density of iNOS+ cells (a marker of anti-tumor M1 tumor-associated macrophages) and Granzyme B+ cells." (PMID 31137480, 2019). "Examination of tumor cryosections in an MT1-MMP antibody treated MDA-MB-231 triple-negative breast cancer xenograft mouse model revealed an increased density of iNOS+ cells (a marker of anti-tumor M1 tumor-associated macrophages) and Granzyme B+ cells." (PMID 31461880, 2019). "Here, we demonstrated that F1 leads to NK cell activation via IL-15 upregulation, associated with increased granzyme B and perforin production to eliminate tumor cells, as well as higher levels of the antitumor IFNγ cytokine." (PMID 30717773, 2019).
tumor (continued). "To further characterize the phenotype of tumor-associated neutrophils, we assessed the expression of GZMB, an arm used by NK and cytotoxic CD8 T-lymphocytes cells to kill their targets." (PMID 29983866, 2018). "First, while GzmB−/− CD8+ T cells exhibit reduced ability to cause GVHD, which was expected, surprisingly GzmB−/− CD8+ T cells showed significantly enhanced GVT activity with several tumor models." (PMID 30631325, 2018). "In contrast, favorable clinical response to anti-PD-1 therapy was, among others, associated with enhanced expression of granzyme B on tumor-infiltrated CD8(+) cytotoxic T cells (CTLs)." (PMID 30631358, 2018). "We showed that even if T cells secreting GzmB, TNFa, and IFNg were more numerous the cytotoxicity produced by cNK populations against the tumor was higher in RBPJ-deficient mice, even after T cell transfer." (PMID 29930552, 2018). "Further, double immunostaining of GZMB and M30, a hallmark of apoptosis, demonstrates that apoptotic tumor cells in treated rats contained GZMB." (PMID 29983866, 2018). "The cytotoxic CD8+ T cells are well known for their anti-tumor immunity, whereby they respond to tumor-associated antigens by releasing cytotoxic molecules, such as granzyme B and perforin." (PMID 30453514, 2018). "Inflammation has been reported to increase tumor formation and loss of IL-15 promoted tumor development in the Granzyme B Tax model." (PMID 29050201, 2017). "We evaluated 4, 12 and 18-month cohorts of Granzyme B HBZ (Gzmb-HBZ) mice for tumor formation and bone loss." (PMID 29050201, 2017). "To identify additional immune cells that are key in tumor immunity, we counted granzyme B+ CD8 T cells and mature dendritic cell lysosomal-associated membrane protein (DC-LAMP, CD208) APC inside TLO." (PMID 28567040, 2017). "Granzyme B (GrB) is a serine protease traditionally known as molecule expressed by cytotoxic lymphocytes to cause apoptosis in tumor and virally infected cells, primarily by activation of caspase-driven pathways." (PMID 26830472, 2016). "Activated CD8+ T cells have been shown to migrate to the tumour microenvironment and cause lysis of tumour cells mediated by granzyme B, perforin or Fas." (PMID 24520352, 2014). "Expression of high levels of Fas Ligand, perforin, and granzyme B by iNKT cells underlies their cytolytic activity against CD1d+ tumor cells and myeloid cells with immunosuppressive function present in the tumor microenvironment." (PMID 25349699, 2014). "Using a system of tumor inoculation and adoptive transfer of Tregs, it was shown that GzmB was highly induced in tumor-associated Tregs by local factors in the tumor microenvironment." (PMID 22890822, 2013). "In murine systems, a fraction of tumor-associated Tregs express Granzyme B, and this molecule also appears to contribute to Treg mediated suppression." (PMID 22319577, 2012). "The mechanism by which activated NK cells kill membrane Hsp70-positive tumor cells is associated with an enhanced production and release of the pro-apoptotic serine protease Granzyme B (grB)." (PMID 22829941, 2012). "Intratumoral CTLs secreted cytolytic pore-forming perforins and granzyme B proteins near the surface of carcinomas, causing the death of many tumor cells." (PMID 21311755, 2011). "Trastuzumab treatment was associated with significantly increased numbers of tumour-associated NK cells and increased lymphocyte expression of Granzyme B and TiA1 compared with controls." (PMID 16404427, 2006). "The enhanced NK-mediated tumor lysis promoted by tuvusertib was not only due to immunogenic modulation on tumor cells but was also associated with increased perforin and granzyme B expression on the N-803-stimulated NK cell population when co-cultured with tuvusertib-treated cells." (PMID 41417226, 2025).